ZIC4 (Zic family zinc finger 4)
Diseases named in the same sentence as ZIC4 in open-access papers (continued):
Sharing a sentence is not in itself a finding about the gene and the disease.
anencephaly (1 paper, 2020). A rare neural tube defect during pregnancy, resulting in the absence of a large portion of the brain and skull in the fetus. "Increased risk for spina bifida and anencephaly, two major subtypes of NTDs, was also in association with ZIC4 hypomethylation." (PMID 33304900, 2020).
autoimmune encephalitis (1 paper, 2025). Inflammation of the brain secondary to an immune response triggered by the body itself. "Negative autoimmune encephalitis panel antibodies, including NMDA receptor, AMPA receptors 1 and 2, LGI1, anti-Ma2/Ta, anti-Hu, anti-Ri, anti-Yo, and anti-Zic4, ruled out paraneoplastic or autoimmune encephalitic syndromes." (PMID 40909059, 2025).
autonomic dysfunction (1 paper, 2020). "Despite considerable therapeutic efforts, the patient passed away on autonomic dysfunction, highlighting the significance of Zic4 associated disease." (PMID 32450842, 2020).
Brain atrophy (1 paper, 2022). Partial or complete wasting (loss) of brain tissue that was once present. "The abnormalities in our cohort's brain MRIs were unspecific, i.e., there was no general brain atrophy or cerebral microangiopathy-more evidence that our patients with delirium and NMDAR and Zic4 autoantibodies present no relevant brain damage." (PMID 35711589, 2022).
cerebellar ataxia (1 paper, 2024). A neurological syndrome characterized by clumsy and uncoordinated movement of the limbs, trunk, and cranial muscles. "In the cerebellar irAE cohort, patients demonstrated Ab positivity to uncharacterized antigens, high risk Abs, and Abs which have shown association to cerebellar ataxia, though remaining less characterized (anti-TRIM9, neurofilament-light chain, and anti-Zic4)." (PMID 39153058, 2024).
cerebellar malformation (1 paper, 2024). Cerebellar malformations are diverse congenital anomalies frequently associated with developmental disability. "Heterozygous deletions encompassing the ZIC4 locus are associated with a rare congenital cerebellar malformation known as the Dandy–Walker malformation." (PMID 39348415, 2024).
choroid plexus carcinoma (1 paper, 2024). A malignant neoplasm arising from the choroid plexus. "Hyper-methylation of ZIC4 was confirmed in a choroid plexus carcinoma-derived cell line (CCHE-45) by bisulfite sequencing." (PMID 39266576, 2024).
choroid plexus tumors (1 paper, 2024). "However, understanding the regulation and function of ZIC4 in pediatric choroid plexus tumors (CPTs) remained limited." (PMID 39266576, 2024).
ciliopathy (1 paper, 2025). A genetic disorder of the cellular cilia or the cilia anchoring structures, the basal bodies, or of ciliary function. "DWS is classified as part of the ciliopathy spectrum, with mutations in genes such as ZIC1, ZIC4, and FOXC1 identified in familial cases." (PMID 41585016, 2025).
delirium (1 paper, 2022). A disorder characterized by confusion; inattentiveness; disorientation; illusions; hallucinations; agitation; and in some instances autonomic nervous system overactivity. "We detected NMDAR and Zic4 antibodies in the serum of delirium patients suggesting possible CNS inflammation." (PMID 35711589, 2022).
head and neck squamous cell carcinoma (1 paper, 2017). A squamous cell carcinoma that arises from any of the following anatomic sites: lip and oral cavity, nasal cavity, paranasal sinuses, pharynx, larynx, and salivary glands. "In summary, we report that CXXC4, DACT2, HHIP, ZIC1, and ZIC4 are methylated in head and neck squamous cell carcinomas." (PMID 27553089, 2017).
Hydrocephalus (1 paper, 2019). Hydrocephalus is an active distension of the ventricular system of the brain resulting from inadequate passage of CSF from its point of production within the cerebral ventricles to its point of absorption into the systemic circulation. "The cerebral cortex of Zic4Cre;Ext1Fl/Fl brains was thinned and the ventricles were enlarged and this hydrocephalus-like phenotype is intriguing because the cerebral cortex is not of the Zic4 lineage, indicating a non-cell-autonomous mechanism by which HS regulates cerebral cortex development." (PMID 30617207, 2019).
leukemia (1 paper, 2024). A malignant (clonal) hematologic disorder, involving hematopoietic stem cells and characterized by the presence of primitive or atypical myeloid or lymphoid cells in the bone marrow and the blood. "Their associated antibodies were anti-Recoverin with T cell lymphoma, multiple antibodies (anti-Yo, anti-ZIC4, anti-NMDAR) with TCC, and anti-GAD65 with leukemia." (PMID 39624101, 2024).
liver cancer (1 paper, 2020). An epithelial or non-epithelial malignant neoplasm that arises from the liver. "The results also pointed that epigenetic silencing of ZIC4 by EZH2 mediated H3K27me3 is an important mechanism in human liver cancer, which are very important for subsequent clinical research." (PMID 33097694, 2020). "Our study indicated that epigenetic silencing of ZIC4 by EZH2 mediated H3K27me3 is an important mechanism in human liver cancer." (PMID 33097694, 2020).
olivopontocerebellar atrophy (1 paper, 2022). A group of sporadic and inherited neurodegenerative disorders affecting the cerebellum, pons, and inferior olives. "Strong immunohistochemical expression of ZIC4 was detected in a subset of neurons of the dentate nucleus in all healthy controls and in patients with striatonigral degeneration, whereas ZIC4-immunoreactive neurons were significantly reduced inpatients with olivopontocerebellar atrophy." (PMID 35997131, 2022).
oropharyngeal tumors (1 paper, 2017). "The methylation of ZIC4 may be considered a new prognostic marker in oral cavity and oropharyngeal tumors." (PMID 27553089, 2017).
parotid cancer (1 paper, 2025). "In our patient, the Zic4 antibody was found to bind to the intracellular nucleolus of the parotid cancer cell, supporting this theory." (PMID 40959352, 2025).
parotid tumor (1 paper, 2025). "Additionally, the presence of both a parotid tumor and the Zic4 antibody supported the classification of this case as definite PNS." (PMID 40959352, 2025).
prostate carcinoma (1 paper, 2016). A carcinoma that arises from epithelial cells of the prostate gland. "Interestingly, we found that ZIC1, ZIC2, ZIC4 and ZIC5 were all up-regulated in Gleason grade 3 embedded in GS 4 + 3 = 7 prostate cancer on RNA level." (PMID 27191985, 2016).
ptosis (1 paper, 2024). The drooping of the upper eyelid. "Anti-Zic4 antibodies were identified in a man who presented with diplopia, muscle stiffness, and fluctuating eyelid ptosis." (PMID 38541012, 2024).
small cell carcinoma (1 paper, 2023). A neuroendocrine carcinoma composed of small malignant cells which are often said to resemble "oat cells" under the microscope. "Consistent with the immune response against multiple neural antigens encountered in small cell carcinoma, she was also positive for Hu, SOX-1, and ZIC4 by line blot." (PMID 37841252, 2023).
Vertigo (1 paper, 2025). An abnormal sensation of spinning while the body is actually stationary. "Preoperatively, she experienced symptoms of nausea and vertigo and was later diagnosed with PNS based on the presence of Zic4 antibodies in the cerebrospinal fluid." (PMID 40959352, 2025).
tumor (11 papers, 2012 to 2025). "The integration of RNA-seq and SILAC data provided a prospective understanding of the molecular mechanisms underlying ZIC4's tumor suppressor role in CPTs." (PMID 39266576, 2024). "Ultimately, these findings underscore ZIC4 hyper-methylation as a prognostic marker in CPTs and shed light on potential mechanisms underlying its tumor suppressor role in CPC." (PMID 39266576, 2024). "Further analysis of oncogenes and tumor suppressor genes revealed that tumors exhibited elevated expression of oncogenes such as ZWINT and ZIC4, and decreased expression of tumor suppressors like HAMP and CXCL14." (PMID 41388520, 2025). "ZIC4 has been described to be epigenetically silenced in many types of cancers which was correlated with poor prognosis, and was shown to have a tumor suppressor function by being involved in pathways like Shh and notch pathways." (PMID 39266576, 2024). "Immunohistochemistry showed that the Zic4 antibody stained the nucleoli of tumor cells." (PMID 40959352, 2025). "Immunohistochemistry revealed that the Zic4 antibody stained the nucleoli of tumor cells." (PMID 40959352, 2025). "This indicates that ZIC4 over-expression may disrupt metabolic reprogramming essential for tumor cell proliferation." (PMID 39266576, 2024). "ZIC4 exerts tumor suppressor activity in CCHE-45 by up-regulating genes involved in immune response modulation pathways such as RIGI-like receptor signaling and IFN signaling, as well as influencing genes and proteins associated with oxidative stress and metabolic pathways." (PMID 39266576, 2024). "The genome-wide methylation data of an independent dataset (The Cancer Genome Atlas) consisting of 50 HCC samples and their matched surrounding tissues were employed and found that ZIC4 was hypermethylated in tumor tissues compared to normal tissues in the top 30 candidate genes." (PMID 33097694, 2020). "In addition, for HCC orthotopic implantation mouse models, in vivo imaging system (IVIS) showed that tumor growth was significantly suppressed after DZNep treatment and tumor growth was significantly promoted after ZIC4 knockdown." (PMID 33097694, 2020). "Higher ZIC4 methylation in tumor tissues compared to paired normal tissues was displayed." (PMID 33097694, 2020). "Frag_01, Frag_02 and ZIC4 present a much lower P-value, indicating they may be better tumor markers than CDKN2A and RASSF1." (PMID 22726460, 2012). "Moreover, by re-expressing ZIC4 in CPC cells, we could identify a set of key molecular targets involved in its tumor suppressor function in the context of CPTs." (PMID 39266576, 2024). "We added ZIC4 because it was one of the DMRs not yet reported as methylated in NSCLC and presented a high difference in relative methylation score between lung and tumor samples." (PMID 22726460, 2012).
cancer (10 papers, 2012 to 2025). A tumor composed of atypical neoplastic, often pleomorphic cells that invade other tissues. "ZIC1 and ZIC4 genes are frequently subject to epigenetic silencing through DNA hypermethylation at their promoter regions in several cancers." (PMID 40952541, 2025). "Zic family member ZIC4 is a transcription factor that has been shown to be silenced in several cancers." (PMID 39266576, 2024). "Our second patient with autoantibodies presented the paraneoplastic Zic4 antibody, supporting his potential for cancer-related immunity." (PMID 35711589, 2022). "ZIC4 methylation was correlated to cancer aggressiveness and could, therefore, be used as a prognostic molecular marker." (PMID 39266576, 2024). "Using an in vitro model system to understand the underlying mechanisms and pathways involved, we could show that epigenetic silencing of ZIC4 is essential for establishing key cancer hallmarks such as increased proliferation, migration, and potential immune evasion." (PMID 39266576, 2024). "Inspired by previous reports suggesting a paraneoplastic etiology in rare cases of cancer-associated NMOSD, this is the first study systematically investigating the seroprevalence of onconeural antibodies (anti-Hu, Yo, Ri, CV2/CRMP5, Ma1, Ma2, Zic4, SOX1, Tr, and amphiphysin) in NMOSD patients." (PMID 28068933, 2017). "We identified 30 cancer-specific normal-invariant genes, including Zic family members (ZIC1, ZIC4, and ZIC5), DPPA2, PRSS56, ELF5, and FGF18, most of which were cancer-associated genes." (PMID 39969322, 2024). "Presently, cancer angiogenesis research is mainly focused on VEGF, but some studies have identified that circRNA can regulate cancer angiogenesis via AGGF1, ZIC4, and SOX13." (PMID 37616050, 2023). "ZIC1 and ZIC4 are known to be regulators of the SHH signaling pathway by antagonizing the transcriptional activity of Gli proteins, and arefound to be silenced by hypermethylation in several types of cancers." (PMID 40952541, 2025). "The impact of reintroducing ZIC4 on innate immune response in our model system could also be seen with other zinc finger proteins, like BNC2 (human basonuclin 2) and ZNF395 in cancer cells." (PMID 39266576, 2024). "We selected novel epigenetic markers including NKIRAS1/RPL15, THRB RBPS3 (CTDSPL), IQSEC1, NBEAL2, ZIC4, LOC285205, CGGBP1, EPHB1 and FOXP1 that allowed detection of cancer in ovarian biopsies on all stages with sensitivity equal to (72 ± 11)% and specificity (94 ± 5)%." (PMID 23202957, 2012). "ZIC4 antibodies were initially described in patients with SCLC without PNS and later in a patient with subacute cerebellar ataxia without cancer." (PMID 32760403, 2020).
adenocarcinoma (1 paper, 2025). A common cancer characterized by the presence of malignant glandular cells. "Our case represents the first reported instance of Anti-Hu-associated PCD in a patient with adenocarcinoma of Müllerian origin and one of very few cases involving Anti-Zic4 antibodies in this malignancy." (PMID 40687917, 2025).
ZIC4 also shares sentences with these, for which no sentence is quoted: autoimmune disease (2 papers); encephalitis (2); Cerebellar hypoplasia (1); craniosynostosis (1); Creutzfeldt-Jakob disease (1); dementia (1); dementia with Lewy bodies (1); desmoid tumor (1); diffuse large B-cell lymphoma (1); Distichiasis (1); gastric cancer (1); lung carcinoma (1); microcephaly (1); multiple sclerosis (1); neural tube defect (1); neurodegenerative disease (1); neurodevelopmental disorder (1); neurological disorders (1); neuropathy (1); ovarian teratoma (1); ovarian tumors (1); Papillary Thyroid Carcinoma (1); Paraneoplastic Neurological Syndromes (1); polyneuropathy (1); psychosis (1); rheumatoid arthritis (1); spina bifida (1); striatonigral degeneration (1); systemic lupus erythematosus (1); T cell lymphoma (1).